PYCR1 (pyrroline-5-carboxylate reductase 1)
Diseases named in the same sentence as PYCR1 in open-access papers (continued):
Sharing a sentence is not in itself a finding about the gene and the disease.
hepatocellular carcinoma (20 papers, 2019 to 2024). A malignant tumor that arises from hepatocytes. "It should be noted however that others have shown that supplementation of growth medium with NADP+ is sufficient to rescue loss on PYCR1 expression in hepatocellular carcinoma cells, suggesting altered redox balance following inhibition of proline biosynthesis." (PMID 35130302, 2022). "In particular, the transcription of the PYCR1 gene was only observed in the Huh7.5 hepatocyte cancer line, indicating it to be a possible marker of hepatoma cells." (PMID 37189460, 2023). "In Huh7.5 hepatoma cells, the expression of proteins synthesizing proline from P5C (PYCR1, PYCR2, PYCR3) prevails over proline-utilizing proteins (PRODH and PRODH2) and the coordinated action of PYCR3, PRODH, and PRODH2 proteins." (PMID 37189460, 2023). "For example, previous research demonstrated that silencing of PYCR1 inhibited proliferation, invasive migration capability, epithelial-mesenchymal transition, and metastatic abilities in hepatocellular carcinoma (HCC)." (PMID 37340189, 2023). "When the expression of PYCR1 was downregulated, it enhanced the inhibitory effect of SK on hepatoma cells." (PMID 36119513, 2022). "PYCR1 has also been investigated in hepatocellular cancer, where PYCR1 interference reduced cell growth and survival both in vitro and in vivo." (PMID 35105345, 2022). "A study suggested that miR-2355-5p, miR-3150a-3p, and miR-5000-3p are candidate miRNAs that regulate PYCR1 expression in hepatocellular carcinoma; additional qRT‒PCR results indicated that miR-2355-5p may be an upstream regulator of PYCR1 mRNA24." (PMID 39294443, 2024). "SK downregulating PYCR1 might supply a theoretical foundation for the potential therapeutic application in hepatocellular carcinoma." (PMID 35293266, 2022). "However, the effect of SK and PYCR1 on apoptosis and autophagy in hepatocellular carcinoma are unclear." (PMID 35293266, 2022). "Another group observed that PYCR1 gene silencing could inhibit the proliferation of hepatoma cells, promote apoptosis, and significantly inhibit the volume and size of transplanted tumors in nude mice by regulating the JNK/IRS1 pathway." (PMID 35293266, 2022). "In contrast, PYCR1 interference inhibits cell growth and survival in hepatocellular cancer." (PMID 33461172, 2021). "Additionally, another reports demonstrated that PYCR1 interference inhibited cell proliferation and enhanced cell apoptosis in hepatocellular carcinoma by repressing JNK/IRS1 pathway." (PMID 33062641, 2020). "Therefore, it is necessary to explore the mechanisms of PYCR1 on cell growth and survival in hepatocellular carcinoma (HCC)." (PMID 31619254, 2019). "Furthermore, recent studies have also reported that PYCR1 is up-regulated in human cancers, and thus promote the progression of cancers including non-small-cell lung cancer, prostate cancer, and hepatocellular cancer, among others." (PMID 33062641, 2020). "This aligns with research indicating PYCR1 in tumors such as colorectal cancer, bladder cancer, and gastric cancer, among others, and PYCR2 in colorectal cancer, hepatocellular carcinoma, melanoma, and other cancers." (PMID 39125668, 2024). "Increasing evidence suggests that PYCR1 is highly expressed in various cancers, such as prostate cancer, non-small cell lung cancer (NSCLC) and hepatocellular cancer." (PMID 37340189, 2023). "Overexpression of PYCR1 has also been shown in bladder cancer, gastric cancer, NSCLC as well as hepatocellular cancer." (PMID 35105345, 2022). "As previously, evidences have revealed that PYCR1 dramatically enhanced cell growth and survival through activating JNK/IRS1 pathway in the development of hepatocellular cancer." (PMID 34696668, 2021). "The downregulation of PYCR1 dramatically repressed cell growth and survival by inactivating the c-Jun N-terminal kinase/insulin receptor substrate 1 (JNK/IRS1) pathway in hepatocellular cancer cells." (PMID 34696668, 2021).
hepatocellular carcinoma (continued). "Increased expression of PYCR1 has since been confirmed in different cancers, including melanoma, NSCLC, renal cell carcinoma, breast cancer, colorectal cancer, prostate cancer, hepatocellular carcinoma, and isocitrate dehydrogenase 1 (IDH1)-mutant gliomas." (PMID 33083024, 2020). "In literature, PYCR1 interference has been shown to decrease p-AKT levels in bladder cancer cell lines, papillary renal cell carcinoma and in melanoma, while it also reduces cell growth in hepatocellular cancer cell lines." (PMID 35105345, 2022). "The Cancer Genome Atlas (TCGA) database and gene expression profiles from a Singapore-based cohort reveal that PYCR1 and ALDH18A1 are among the most up-regulated genes in Hepatocellular Carcinoma (HCC)." (PMID 32500033, 2020). "Overexpression of pyrroline-5-carboxylate reductase 1 (PYCR1) has been associated with the development of certain cancers; however, no studies have specifically examined the role of PYCR1 in hepatocellular carcinoma (HCC)." (PMID 34239351, 2021). "Other pathways shown to be altered by PYCR1 interference are the p38 MAPK pathway in NSCLC and the IRS1/JNK pathway in hepatocellular cancer, although we could not confirm this in MM (data not shown)." (PMID 35105345, 2022).
prostate carcinoma (18 papers, 2012 to 2024). A carcinoma that arises from epithelial cells of the prostate gland. "Recent studies demonstrated that miR-1207-5p and miR-328-3p suppressed the progression of prostate cancer and lung adenocarcinoma by targeting PYCR1." (PMID 35731336, 2022). "They found that a low expression of PYCR1 resulted in the inhibition of cell proliferation and colony formation, cell cycle arrest, and apoptosis in prostate cancer cells." (PMID 36119513, 2022). "PYCR1 has been reported to be upregulated in many human cancers, including prostate cancer, thereby promoting cancer progression." (PMID 34868460, 2021). "However, animal experiments indicated that there were certain correlations in prostate cancer, colorectal cancer, and melanoma, that is to say, PYCR1 knockdown inhibited cancer progression." (PMID 36119513, 2022). "In prostate cancer, previous studies revealed the possible mechanism of PYCR1 in tumorigenesis." (PMID 35371311, 2022). "Previous studies have reported that PYCR1, a proline biosynthetic enzyme, was up-regulated in prostate cancer (PCa) compared with normal tissues and it could also promote PCa cell proliferation and colony formation." (PMID 31772843, 2019). "A recent study found that expression of PYCR1 is up-regulated in prostate cancer." (PMID 23024808, 2012). "Moreover, emerging evidence suggests that PYCR1 is upregulated and plays a protumor role in several different types of cancers, including non-small cell lung cancer, breast cancer, gastric cancer, colorectal cancer, hepatocellular carcinoma, prostate cancer and bladder cancer." (PMID 38023181, 2023). "Up-regulation of mitochondrial PYCR1 and PYCR2 is observed in a number of cancer types, such as prostate cancer and lymphoma." (PMID 34822010, 2021).
bladder cancer (14 papers, 2020 to 2025). "Collectively, these findings further supported that overexpression of BHLHE41 inhibited bladder cancer growth in vivo, which might be associated with the downregulation of PYCR1 and the inactivation of PI3K/AKT signaling pathway." (PMID 38811952, 2024). "RAC3 enhances proliferation and metastasis in bladder cancer cells by activating the JAK/STAT signaling pathway mediated by PYCR1." (PMID 40123831, 2025). "Altogether, these results suggested that BHLHE41 inhibited bladder cancer progression via PYCR1/PI3K/AKT signaling pathway." (PMID 38811952, 2024). "In summary, we examined the expression level and the role of BHLHE41 in bladder cancer, and identified that BHLHE41 inhibited bladder cancer progression via regulation of PYCR1 stability and thus inactivating of PI3K/AKT signaling pathway." (PMID 38811952, 2024). "BHLHE41 played a suppressive role in the progression of bladder cancer via regulation of PYCR1 stability and thus inactivation of PI3K/AKT signaling pathway." (PMID 38811952, 2024). "RAC3 is highly expressed in bladder cancer cells, and stimulates proliferation and migration of bladder cancer cells via PYCR1-mediated JAK/STAT pathway activation." (PMID 37056933, 2023). "Compared with normal bladder samples, the protein expression of PLOD1, ATP6V1B1, HSD17B1, SERPINB7, and PYCR1 in bladder cancer tissues was upregulated, while EGR1 in cancer tissues was down-regulated." (PMID 37880682, 2023). "PYCR1 catalyses the reduction of P5C to proline, and high expression of PYCR1 has been reported in other cancer types, including bladder cancer, gastric cancer, etc.." (PMID 36978187, 2023). "Ubiquitin-specific peptidase 18 (USP18) upregulates FTO levels through post-translational deubiquitination while decreasing m6A levels in PYCR1, thereby stabilizing the PYCR1 transcript and promoting bladder cancer initiation and progression." (PMID 37391814, 2023). "Next, we found that knockdown of PYCR1 inhibited Epithelial to mesenchymal transition of bladder cancer, and simultaneously mitigated the carcinogenic effects of STAT3." (PMID 36227136, 2022). "STAT3 in the nucleus upregulated the expression of oncogene pyrroline-5-carboxylate reductase 1 (PYCR1), which promoted bladder cancer proliferation and EMT." (PMID 36227136, 2022). "Recent study has found that PYCR1 is highly expressed in bladder cancer; depletion of PYCR1 in turn suppresses proliferation and invasion of bladder cancer." (PMID 36227136, 2022). "As a result, FTO decreased N6-methyladenosine methylation level in PYCR1 through its demethylase enzymatic activity and stabilized PYCR1 transcript to promote bladder cancer initiation and progression." (PMID 33461172, 2021). "The BHLHE41/PYCR1/PI3K/AKT axis might be a potential therapeutic target for bladder cancer intervention." (PMID 38811952, 2024). "Therefore, it can be assumed that STAT3 as a transcription factor has the function of activating PYCR1 in bladder cancer." (PMID 36227136, 2022). "In addition, PYCR1 is up-expressed in numerous malignancies, including bladder cancer, breast cancer, renal cell cancer and lung cancer." (PMID 36227136, 2022). "The results provide novel insights into the regulation of SENP3/STAT3/PYCR1 pathway, which has key roles in bladder cancer progression and may aid in identifying new biomarkers or targeted therapies for bladder cancer." (PMID 36227136, 2022). "Our team have found that PYCR1 is highly expressed in bladder cancer and has an oncogene function." (PMID 36227136, 2022). "We sought to clarify how SENP3 affects PYCR1 and STAT3 to regulate the development of bladder cancer." (PMID 36227136, 2022). "Knock-down of PYCR1 inhibited the viability, proliferation, invasion and EMT of bladder cancer cells that were induced by STAT3." (PMID 36227136, 2022). "SENP3/STAT3/PYCR1 pathway promoted the viability, proliferation, invasion and EMT of bladder cancer cells." (PMID 36227136, 2022).
bladder cancer (continued). "Our work shows the importance of N6-methyladenosine RNA modification in bladder cancer development, and highlights UPS18/FTO/PYCR1 signaling network as potential therapeutic targets of bladder cancer." (PMID 33461172, 2021). "Pyrroline-5-carboxylate reductase 1 (PYCR1), a well-documented tumor promoting factor, attracted our attention since it was reported to be dysregulated in bladder cancer and might be participated in regulating PI3K/AKT pathway." (PMID 38811952, 2024).
lung adenocarcinoma (13 papers, 2019 to 2024). A carcinoma that arises from the lung and is characterized by the presence of malignant glandular epithelial cells. "In the case of lung adenocarcinoma cell cultures, PYCR1 silencing has been associated with increased cisplatin sensitivity." (PMID 38275897, 2024). "This study explored the role of PYCR1 in the physiological behavior of lung adenocarcinoma and the potential mechanism underlying the tumor cell resistance to cisplatin, which provided novel insights into lung adenocarcinoma to formulate strategies for the treatment." (PMID 31143549, 2019). "When treating lung adenocarcinoma cells with cisplatin in PYCR1-silenced/vehicle control/blank control groups, cisplatin stimulation significantly increased cell proliferation in PYCR1-silenced group when compared to the vehicle control." (PMID 36119513, 2022). "And PYCR1 inhibition with Kindlin-2 inhibited proline synthesis and cell proliferation, and increased ROS production and apoptosis in lung adenocarcinoma cells." (PMID 35731336, 2022). "KO of PINCH-1 from human lung adenocarcinoma cells in culture as well as lung adenocarcinoma in mouse reduced the levels of PYCR1 and proline." (PMID 33004813, 2020). "Accordingly, lung adenocarcinoma cell sensibility to cisplatin increased upon PYCR1 silencing, further supporting the idea that PYCR1 is a potential therapeutic target for lung adenocarcinoma." (PMID 32500033, 2020). "Next, the lung adenocarcinoma cell invasion analysis by Transwell chamber system demonstrated that PYCR1-silenced lung adenocarcinoma cells showed a significant reduction in the invasion ability." (PMID 31143549, 2019). "Ablation of kindlin-2 in lung adenocarcinoma substantially reduces PYCR1 and proline levels, and diminishes fibrosis in vivo, resulting in marked inhibition of tumor growth and reduction of mortality rate." (PMID 30783087, 2019). "The results demonstrated significant differences between the vector control group and the PYCR1-silenced lung adenocarcinoma NCI-H1299 cells after 24 h post-scratch (P < 0.05), whereas the variation in the migration rate was <20%." (PMID 31143549, 2019). "The PYCR1 gene promotes the physiological behaviors such as proliferation and invasion of lung adenocarcinoma cells." (PMID 31143549, 2019). "This study is the first to explore the effect of PYCR1 gene on migration, invasion, and cisplatin sensitivity of lung adenocarcinoma, and confirmed that PYCR1 gene promoted the invasion and caused cisplatin resistance." (PMID 31143549, 2019). "This study found that the PYCR1 gene is highly expressed in lung adenocarcinoma cells, and is positively correlated with the pathological grade of lung adenocarcinoma." (PMID 31143549, 2019). "The results demonstrated the PYCR1-silencing led to a rise in cisplatin sensitivity in lung adenocarcinoma cells." (PMID 31143549, 2019). "The CCK8 assay was performed to detect the proliferation and cisplatin sensitivity, while the effect of PYCR1 on the migration and invasion of lung adenocarcinoma cells was detected by scratch test and transwell chamber assay." (PMID 31143549, 2019). "Both kindlin-2 and PYCR1 levels were markedly increased in cancerous tissues compared with those in normal tissues adjacent to lung adenocarcinoma." (PMID 30783087, 2019). "Consistent with this, kindlin-2 also interacts with PYCR1 in mesenchymal stem cells (MSCs), and similar to what we found in lung adenocarcinoma cells, the kindlin-2–PYCR1 interaction in MSCs is enhanced in response to ECM stiffening." (PMID 30783087, 2019). "In the current study, we show that genetic ablation of kindlin-2 is sufficient to inhibit the increases of the levels of PYCR1, proline, and collagen matrix in lung adenocarcinoma and reduces tumor burden and mortality rate in vivo." (PMID 30783087, 2019). "In vivo, both kindlin-2 and PYCR1 levels are significantly increased in lung adenocarcinoma, which is of greater stiffness compared with that of healthy lung tissues." (PMID 30783087, 2019).
lung adenocarcinoma (continued). "This study demonstrated that silencing the PYCR1 gene can enhance the sensitivity to cisplatin that rendered PYCR1 as a promising candidate target for the treatment of lung adenocarcinoma." (PMID 31143549, 2019). "Again, the levels of kindlin-2 and PYCR1 were markedly increased in KrasG12D-induced lung adenocarcinoma compared with those in normal mouse lung tissues." (PMID 30783087, 2019). "To do this, we first analyzed the levels of kindlin-2 and PYCR1 in human lung adenocarcinoma by immunohistochemical staining." (PMID 30783087, 2019). "Collectively, these results suggest that the levels of kindlin-2 and PYCR1 are elevated, which are correlated with increased stiffness in lung adenocarcinoma in vivo." (PMID 30783087, 2019). "To confirm this, we analyzed the levels of kindlin-2 and PYCR1 in KrasG12D-induced lung adenocarcinoma in mice." (PMID 30783087, 2019). "The results indicated that PYCR1 silencing could increase cisplatin sensitivity to lung adenocarcinoma cells." (PMID 36119513, 2022). "Interestingly, SIRT3 regulates proline synthesis by deacetylation of PYCR1 enzyme protein and increasing proline synthesis, and knockdown of PYCR1 in lung adenocarcinoma inhibits the proliferation and invasion by modulating JAK/STAT." (PMID 34825974, 2021). "Furthermore, CCK8 assay demonstrated that PYCR1-silencing significantly inhibited the cell proliferation in lung adenocarcinoma." (PMID 31143549, 2019). "In vivo, both kindlin-2 and PYCR1 levels are markedly increased in lung adenocarcinoma." (PMID 30783087, 2019). "In order to explore the role of PYCR1 in tumor cell resistance to cisplatin, lung adenocarcinoma cells in PYCR1-silenced/vector control/blank control groups were treated with cisplatin at different concentrations, followed by detection of inhibition of the proliferation using the CCK8 assay." (PMID 31143549, 2019). "Hitherto, PYCR1-silencing lung adenocarcinoma cells were established successfully." (PMID 31143549, 2019). "This indicated that PYCR1-silencing inhibited the proliferation of lung adenocarcinoma cells." (PMID 31143549, 2019). "Using a conditional knockout (KO) strategy, ablation of kindlin-2 from lung adenocarcinoma in mice markedly reduces the levels of PYCR1 and proline, diminished fibrosis, and inhibited tumor growth in vivo, resulting in significant reduction of the mortality rate." (PMID 30783087, 2019). "Moreover, we established PYCR1-silenced lung adenocarcinoma cells to evaluate the changes in cell proliferation, migration, invasion, cisplatin sensitivity." (PMID 31143549, 2019). "Thus, the future experiments will study the effect of PYCR1-overexpression on the physiological behavior of lung adenocarcinoma in the corresponding cellular and animal experiments." (PMID 31143549, 2019). "Moreover, to probe the effect of differential expression of the gene on the proliferation, migration, invasion, and drug sensitivity of lung adenocarcinoma, we successfully established the PYCR1-silenced lung adenocarcinoma cells." (PMID 31143549, 2019). "Therefore, we consider that the PYCR1 gene may influence the biological behavior of lung adenocarcinoma cells by regulating cell energy/material metabolism, and this is also our next research direction." (PMID 31143549, 2019). "This might be due to the fact that the PYCR1 has little effect on simple horizontal movement of lung adenocarcinoma cells, but can regulate some substances, which led to the remodeling and degradation of extracellular matrix, thereby enhancing the invasiveness of cells." (PMID 31143549, 2019). "Therefore, it can be speculated that the PYCR1 gene affects the biological behavior of lung adenocarcinoma and cisplatin resistance, serving as a potential therapeutic target for lung adenocarcinoma." (PMID 31143549, 2019).